DYNLRB1 (dynein light chain roadblock-type 1)
Description:
Component of dynein, a family of motor proteins essential for movement along microtubules (By similarity). Required for structural and functional integrity of cilia (By similarity). Acts as one of several non-catalytic accessory components of the cytoplasmic dynein 1 complex that are thought to be involved in linking dynein to cargos and to adapter proteins that regulate dynein function (Probable). Cytoplasmic dynein 1 acts as a motor for the intracellular retrograde motility of vesicles and organelles along microtubules (Probable).
Synonyms: BLP; BITH; DNCL2A; DNLC2A; ROBLD1
Tractability: Small molecule: a structure with a bound ligand is known; it has a binding pocket of medium quality. PROTAC: ubiquitination databases record sites on it; its protein half-life has been measured.
Gene: Protein-coding gene on chromosome 20 (34,516,379 to 34,540,958, forward strand). Ensembl gene ENSG00000125971.
Subcellular location: Cytoplasm, cytoskeleton
Pathways (Reactome):
Organelle biogenesis and maintenance: Intraflagellar transport
Gene Ontology:
Molecular function: protein binding; dynein intermediate chain binding; microtubule motor activity; identical protein binding
Biological process: intraciliary retrograde transport; microtubule-based movement; positive regulation of intracellular transport; positive regulation of mitotic cell cycle spindle assembly checkpoint; visual behavior
Cellular component: centrosome; cytoplasmic dynein complex; membrane; ciliary tip; cilium; cytoplasm; dynein complex; cytoskeleton
Genetic constraint (gnomAD): Loss-of-function variants: 6 observed, 13.92 expected, observed/expected ratio (o/e) 0.43, 90% interval 0.23 to 0.85. The upper end of that interval is the gene's LOEUF score, 0.85, which puts it in group 3 of 6, group 1 being the genes least tolerant of losing a copy. Missense variants: 93 observed, 132.36 expected, observed/expected ratio (o/e) 0.7, 90% interval 0.59 to 0.83. Synonymous variants: 43 observed, 46.57 expected, observed/expected ratio (o/e) 0.92, 90% interval 0.72 to 1.19.
Homologues: Orthologues: chimpanzee DYNLRB1 (99% identical), macaque DYNLRB1 (99% identical), mouse Dynlrb1 (97% identical), guinea pig DYNLRB1 (96% identical), rat Dynlrb1 (96% identical), zebrafish dynlrb1 (80% identical), dog DYNLRB1 (69% identical), Caenorhabditis elegans dyrb-1 (48% identical). Paralogues in human: DYNLRB2 (77% identical).
Diseases named in the same sentence as DYNLRB1 in open-access papers:
DYNLRB1 is named in the same sentence as 17 diseases in open-access papers, as found by Europe PMC text mining. Sharing a sentence is not in itself a finding about the gene and the disease. The quoted sentences say what the papers report.
autism (2 papers, 2023 to 2025). Persistent deficits in social interaction and communication and interaction as well as a markedly restricted repertoire of activity and interest as well as repetitive patterns of behavior. "Interestingly, four related proteins, DYNC1I1, DYNC1LI1, DYNC1LI2 and DYNLRB1 were also reduced significantly in cerebellar vermis of children with autism." (PMID 40779003, 2025).
atherosclerosis (1 paper, 2014). A disease characterized by the build-up of fatty material and calcium deposition in the arterial wall resulting in partial or complete occlusion of the arterial lumen. "Microarray data showed Dynlrb1 and Plac9 have lower expression in 129 compared to DBA and B6, although their association with atherosclerosis has not been reported." (PMID 24586312, 2014).
Cognitive impairment (1 paper, 2021). Abnormal cognition is characterized by deficits in thinking, reasoning, or remembering. "DYNLRB1 was found to be associated to neuronal survival, INPP5K was found to be associated to cognitive impairment, ZFHX2 was found to be associated to behavioral abnormalities and CTNND2 was found to be associated to mental retardation and intellectual disability." (PMID 33510859, 2021).
hepatocellular carcinoma (1 paper, 2013). A malignant tumor that arises from hepatocytes. "Similarly, dynein light chain DYNLRB1 is upregulated in patients with hepatocellular carcinoma." (PMID 23840580, 2013).
melanoma (1 paper, 2023). A malignant, usually aggressive tumor composed of atypical, neoplastic melanocytes. "We used the mouse B16-F1 melanoma cell line to investigate the mitotic role of DYNLRB1." (PMID 36973253, 2023).
neurodegenerative disease (2 papers, 2010 to 2023). A disorder of the central nervous system characterized by gradual and progressive loss of neural tissue and neurologic function. "Interestingly, Dynlrb1 was previously shown to reduce mutant huntingtin (mHtt Q74) and α-synuclein (α-syn A53T) aggregation in mouse brain cells, two proteins known for their involvement in neurodegenerative diseases." (PMID 37739344, 2023).
neurological diseases (1 paper, 2023). "We identified the fragile X messenger ribonucleoprotein 1 (FMRP), an RNA-binding protein implicated in neurological disorders, as a Dynlrb1’s interactor and showed that it undergoes retrograde axonal transport with lysosomes in sensory neurons." (PMID 37739344, 2023).
DYNLRB1 also shares sentences with these, for which no sentence is quoted: tumor (4 papers); cancer (3); Alzheimer disease (1); breast carcinoma (1); deafness dystonia syndrome (1); dyslipidemia (1); Intellectual disability (1); microcephaly (1); neurodevelopmental disorder (1); spastic hemiplegia (1).